EGFR (epidermal growth factor receptor)
Diseases named in the same sentence as EGFR in open-access papers (continued):
Sharing a sentence is not in itself a finding about the gene and the disease.
breast carcinoma (continued). "In response to EGF stimulation, the EGFR controls expression of hexokinase (HK1) and phosphorylation of the pyruvate kinase M2 (PKM2), two glycolytic enzymes that catalyze key steps in the pathway, thus increasing aerobic glycolysis of breast cancer cells." (PMID 29124875, 2018). "Breast cancer is divided into several groups according to IHC: ER positive and EGFR negative, HER2 positive which is either ER negative or ER positive and triple negative that is ER, PR, and HER2 negative." (PMID 29978332, 2018). "For example, there are 74 breast cancer-related targets in the Therapeutic Target Database (TTD), including the estrogen receptor (ER), the vascular endothelial growth factor receptor 1 (VEGFR1), and the epidermal growth factor receptor (EGFR)." (PMID 29692857, 2018). "CXCR7 can mediate epidermal growth factor receptor (EGFR) phosphorylation in a CXCR7 ligand-independent way, which enhances EGFR-mediated mitogenic signaling and plays a vital role in proliferation of prostate and breast cancer cells." (PMID 30574021, 2018). "ERα negative breast cancer cells proliferate independently of oestrogen signalling through other signalling pathways such as the EGFR, and downstream PI3K/Akt/mTOR, NF-κB signalling pathways." (PMID 29564971, 2018). "Capsaicin exhibited EGFR signaling-mediated co-carcinogenic effects in chemically induced skin cancer, although capsaicin treatment-related adverse effects in breast cancer studies have not been reported." (PMID 30248941, 2018). "By using the anti-EGFR 2′-Fluoro-pyrimidine (2′F-Py)-RNA CL4 aptamer, previously validated as an efficacious targeting agent in GBM, Her2-positive breast cancer and NSCLC, we demonstrated a novel mechanism of action for this aptamer related with integrin αvβ3-EGFR interaction in TNBC." (PMID 30428522, 2018). "Lapatinib, a dual, reversible HER2/epidermal growth factor receptor (HER1) tyrosine kinase inhibitor, both alone and in combination with chemotherapy, has significantly improved progression-free survival in metastatic HER2+ breast cancer patients." (PMID 29445928, 2018). "Although it has been demonstrated that activation of GPER induces EGFR transactivation in breast cancer cells, there is not much information available in vascular smooth muscle." (PMID 29360846, 2018). "EGFR is a key dimerization partner of HER2, and is frequently expressed in breast carcinomas." (PMID 30279968, 2018). "Epidermal growth factor receptor (EGFR)-positive breast cancer cells, but not negative ones, were induced to invade by ionizing radiation in a reactive oxygen species (ROS)-dependent manner." (PMID 30134800, 2018). "In addition, EGFR deletion can also be detected in malignant gliomas, NSCLC, breast cancer, medulloblastoma and ovarian cancer." (PMID 29455664, 2018). "In breast cancer cell lines, the blockade of EGFR by antibodies or small-molecule inhibitors induces nuclear translocation of FOXO3a and promotes the expression of BNIP3L gene, which consequently results in apoptotic death of breast cancer cells." (PMID 30045773, 2018). "In this project, we showed that disruption of the EGFR/ErbB2-dependent signalling by lapatinib and CP-724714, two inhibitors of the receptor tyrosine kinase (RTK), dramatically reduced the amplitude of the SOCE in breast cancer cells." (PMID 29662626, 2018). "In agreement, we also found CD109 overexpression in the triple negative EGFR overexpressing breast cancer cell line MDA-MB-468, but not in the ER-, PR-, HER2 overexpressing cell line SKBR-3." (PMID 29731998, 2018). "Other pairs of similarly influenced histological tumor types are lung adenocarcinoma and lung squamous cell carcinoma (p = 5.9e−6; proteins: Caveolin1, p70S6K, ACC_pS79, ACC1, Rb_pS807_S811) and breast cancer and ovarian carcinoma (p = 9.0e−6; proteins: HER2_pY1248, HER2, ACC1, EGFR_pY1068)." (PMID 30442178, 2018).
breast carcinoma (continued). "The loss of E-cad expression has been found to be significantly associated with a lack of estrogen receptor (ER) expression, the expression of cytokeratins 5/6 and/or epidermal growth factor receptor (EGFR), and a basal-like phenotype (or triple-negative breast cancer, TNBC) in breast cancer." (PMID 28764784, 2017). "Nevertheless, our results indicate that ZNF516 is a transcription repressor and a potential suppressor of EGFR, adding to the understanding of EGFR-related breast carcinogenesis and supporting the pursuit of ZNF516 as a potential therapeutic target for breast cancer." (PMID 28947780, 2017). "EGFR protein expression has previously been detected in CTCs in early breast cancer and EGFR gene expression was also found in CTCs in non-responders during treatment for MBC." (PMID 28489591, 2017). "In the current study, we found that the expression of ZNF516 is progressively lost during breast cancer progression, and, consistent with our observation that ZNF516 transcriptionally represses EGFR, we showed that the level of ZNF516 expression is negatively correlated with that of EGFR." (PMID 28947780, 2017). "We and other groups reported that NHERF1 could form signaling complexes with PTEN or tyrosine kinase receptors including PDGFR and EGFR to counterbalance AKT and ERK signaling in breast cancer cells." (PMID 28085111, 2017). "Furthermore, they demonstrated that TMEM16A knockdown reduced the autocrine secretion of EGFR ligands, EGF and TGF-α in breast cancer cells, suggesting that TMEM16A can activate EGFR signaling by increasing autocrine secretion of EGFR-ligands." (PMID 28893247, 2017). "In addition, we show, for the first time, that CNR2 activation inhibits the activation of EGFR/IGF-IR signaling pathways and EGF/IGF-I-induced tumorigenic events in ERα- and ERα+ breast cancer subtypes in vitro and in vivo." (PMID 27213582, 2017). "However, in additional to mediating EGFR glycosylation, RPN2 can physically interact with both Y216-phosphorylated and unphosphorylated GSK3β to regulate the malignancy of breast cancer." (PMID 29069815, 2017). "In addition, we showed that EGFR inhibits the expression of miR-338-3p and decreases that of EYA2 in cultured breast cancer cells." (PMID 28703807, 2017). "Thus agents that selectively kill EGFR+ and HER2+ tumors would provide new options for breast cancer therapy." (PMID 28423644, 2017). "We confirmed the specificity of the EGFR and EYA2 antibodies by IHC of breast cancer tissues or immunoblot with cell lysates and that of miR-338-3p staining by correlation analysis of different miR-338-3p expression in breast tissues examined by hybridization and quantitative RT-PCR, respectively." (PMID 28703807, 2017). "In contrast to the robust effects of RBF3 on the EGFR+ or HER2+ breast cancer cell lines, RBF3 and DTT did not induce an ER stress response in wild type Mouse Embryo Fibroblasts (MEFs) and weakly suppressed Akt phosphorylation and induced PARP cleavage." (PMID 28423644, 2017). "We observed that estrogen receptor-α negative (ERα-) breast cancer cells highly express epidermal growth factor receptor (EGFR) as well as insulin-like growth factor-I receptor (IGF-IR)." (PMID 27213582, 2017). "In addition, we identified PHD2 as a binding partner of EGFR and showed that PHD2 acts as a regulator of EGFR signaling and receptor stability in MDA-MB-231 breast carcinoma cells." (PMID 28038470, 2017). "In addition, in ZR75–1 and HCC1954 breast cancer cell lines, the ERK1/2 signaling pathway is activated by TMEM16A overexpression via EGFR and CaMKII." (PMID 28893247, 2017).
breast carcinoma (continued). "Meanwhile, Ca2+-activated Cl− channel transmembrane protein 16A (TMEM16A, also known as ANO1) could promote breast cancer progression by activating calmodulin-dependent protein kinase (CAMK) and epidermal growth factor receptor (EGFR) signaling." (PMID 28264681, 2017). "Breast cancer cells are known to transactivate ERK1/2 through FFA1, involving Src and EGFR." (PMID 28747926, 2017). "In closing, our observations suggest a model by which some threshold of HER2 expression and signaling are required for the formation and/or maintenance of a multi-protein complex that supports prolonged signaling from HER2/EGFR and HER2/HER3 heterodimers in breast cancer cells." (PMID 28369073, 2017). "In summary, the results indicate that a decrease in hydrogen peroxide by CAT-SKL treatment in combination with an EGFR inhibitor holds promise of a novel, therapeutic modality to treat TNBC, a breast cancer subtype with the worst prognosis and high need for treatment options." (PMID 28281569, 2017). "In breast cancer cells, the paracrine role of epidermal growth factor (EGF) and its receptor EGFR (ErbB-1) contribute to invasion, intravasation, and metastasis through activation of extracellular signal-regulated kinase 1/2 (ERK1/2), STAT3, or PI3K/Akt signaling, promoting the EMT." (PMID 29189742, 2017). "In a murine model of breast cancer, TAMs are also demonstrated to promote CSC phenotypes in breast cancer cells through the EGF-mediated STAT3/SOX-2 cascade, and this cross talk could be abrogated by small molecule inhibitors against EGFR or STAT3." (PMID 28337221, 2017). "Additionally, in all four GPR30-positive breast cancer lines, calycosin decreased the phosphorylation levels of SRC, EGFR, ERK1/2 and Akt, but the inhibition of WDR7-7 blocked these changes and increased proliferation." (PMID 29096683, 2017). "It was reported that activation of G protein-coupled receptor 30 (GPR30) induces cells cycle arrest in estrogen receptor negative (ER-) breast cancer cells through EGFR/ERK signal transduction pathway." (PMID 29383186, 2017). "Taken together, these results demonstrated that induction of ACTA2 by EGFR and HER2 dimerization was regulated through a JAK2/STAT1 signaling pathway, and aberrant ACTA2 expression accelerated the invasiveness and metastasis of breast cancer cells." (PMID 28881584, 2017). "It was found that detachment of non-malignant breast cancer cells promotes lysosomal EGFR degradation." (PMID 29285258, 2017). "For example, in ER− breast cancer cells, GPR30 activates the tyrosine kinase SRC through the Gβγ subunit, which stimulates the autophosphorylation of EGFR to initiate MAP-kinase ERK1/2 and phosphatidylinositol 3 kinase (PI3K) signaling, ultimately inducing proliferation." (PMID 29096683, 2017). "Recently, it has been reported that cetuximab, a monoclonal anti-EGFR antibody, reduced mammosphere formation and CSC populations in breast cancer cells in vitro and potentiated the effect of Ixabepilone, a new generation microtubule-stabilizing agent, in treating orthotopic TNBC xenografts." (PMID 28148288, 2017). "Since TMEM16A can form a complex with EGFR and activated the EGFR signaling pathway in HNSCC and breast cancer cells, it remains to be determined whether TMEM16A activates NFκB signaling via EGFR." (PMID 28893247, 2017). "Together, these findings suggest that SRC, EGFR, ERK1/2, and Akt, which are key regulators of cell proliferation and survival in breast cancer cells, act as downstream effectors of the WDR7-7-GPR30 pathway, especially in ER− cells due to the absence of an ER-mediated pathway." (PMID 29096683, 2017). "In addition to the HER2-amplified breast cancer cell line BT474, HER2-MCF7 cells also showed EGFR downregulation by DCA/tamoxifen, suggesting that the combination treatment will be applicable to HER2-postive breast cancer." (PMID 27494858, 2016).
breast carcinoma (continued). "This would suggest that combinatorial treatment, including EGFR‐ and Met‐ as well as PYK2‐inhibitors, might be highly synergistic against certain breast cancer subtypes." (PMID 26506511, 2016). "Consistent with molecular profiles of the cell lines, in all 10 indications with significant numbers of HER2+ samples, EGFR expression was relatively higher and/or ERBB3 and CDKN1B lower in in comparison to breast cancers, and these patterns hold for both the HER2+ and HER2- subsets." (PMID 27035903, 2016). "Moreover, STAT3 is a well-known key pathway downstreamer of EGFR and a promoter to the epithelial to mesenchymal transition (EMT) in breast cancer, through which Anxa 2 promotes EMT in dependence on STAT3 pathway." (PMID 27274723, 2016). "One hundred eighty-four patients with breast cancer received neoadjuvant chemotherapy, and 81 with colorectal cancer received palliative chemotherapy with or without cetuximab, an epidermal growth factor receptor monoclonal antibody." (PMID 27517621, 2016). "With further regard to HER2 in breast cancer, it was found that the EGFR inhibitor gefitinib did not enhance the anti-cancer activity of trastuzumab when used alone." (PMID 26955870, 2016). "Therefore, we evaluate the frequency of co-expression of EGFR and NeuGcGM3 ganglioside in human tumors and in two spontaneous lung metastasis models of mice (Lewis lung carcinoma (3LL-D122) in C57BL/6 and mammary carcinoma (4T1) in BALB/c)." (PMID 27449755, 2016). "The inhibitory effects of integrins on cell growth have also been confirmed by other studies; a deletion of α1β1 integrin enhanced EGFR cellular signaling through a clustering of EGFR18; additionally, the targeting of α2β1 promoted cell growth in some breast cancer cells." (PMID 26728650, 2016). "Moreover, the analyses revealed a mixed epithelial (EGFR+) and mesenchymal (CDH1 null) phenotype for the HBCx-60 (established from metaplastic breast cancer with a spindle cell component)." (PMID 27374081, 2016). "Flow cytometry showed ZEGFR:2377-ST-[DyLight488] (red curves) clearly bound to A431 and less to FaDu, but not at all to MDA-MB-453 cells (human breast carcinoma), which correlated well with EGFR levels (western blot)." (PMID 27388754, 2016). "Clinical trials evaluating the efficacy of anti-EGFR therapy in breast cancer have revealed disappointing outcomes, and correlative studies suggested that EGFR expression/amplification status was not a significant predictor." (PMID 27602761, 2016). "To assess the cytotoxic activity of biparatopic DARPins in vitro, we treated a panel of ErbB2-overexpressing breast cancer cell lines (BT474, HCC1419, HCC2218, SKBR3, AU565 and ZR75-30) with wild-type PI3K activity and a range of EGFR, ErbB3 and PTEN expression levels." (PMID 27255951, 2016). "According to correlation analyses between gene expression and phosphorylated protein expression in both cell lines and tumors, significant results are found that important drug targets in breast cancer, such as ESR1, PGR, HER2, EGFR and AR show high correlated mRNA and protein levels." (PMID 27556158, 2016). "In vitro targeting of EGFR with RTK inhibitors has been reported in the veterinary literature, with successful inhibition of cell proliferation and growth of canine mammary carcinoma and OSA cell lines, further supporting EGFR inhibition as a possible treatment approach for canine OSA." (PMID 27245053, 2016). "The HER2-positive BT-474 breast cancer cell line overexpressing SHP2 and the MCF-10A cells and MEFs ectopically overexpressing HER2 and EGFR were used as positive controls, while parental MCF-10A cells and MEFs as well as HMLE cells were used as negative controls for overexpression." (PMID 26728598, 2016).
breast carcinoma (continued). "In order to preclinically assess the efficacy of anti-EGFR nanobody 99mTc-D10 to detect small tumours in different tumour entities, MDA-MB-468 and MDA-MB-231 human mammary carcinoma cells were implanted orthotopically in the fat pad of the right abdominal mammary gland of nude mice." (PMID 26912069, 2016). "In this paper, we evaluate the co-expression of EGFR and NeuGcGM3 ganglioside in tumors from 92 patients and in two spontaneous lung metastasis models of mice (Lewis lung carcinoma (3LL-D122) in C57BL/6 and mammary carcinoma (4T1) in BALB/c)." (PMID 27449755, 2016). "In fact, we have recently demonstrated important role of Vimentin/Slug EMT markers in tumor growth of primary breast cancer patients and in circulating tumor cells (CTCs) EGFR+ from cytokeratin negative non-metastatic breast cancer patients." (PMID 26752044, 2016). "On the other hand, p-EGFR Tyr1068 expression correlated only with HER2 positive breast cancer cases (p<0.05) and not with TN." (PMID 27055285, 2016). "Furthermore, we demonstrated cancer-derived AREG partially promoted breast cancer growth and migration via an autocrine AREG/EGFR signaling pathway." (PMID 27765922, 2016). "The expression of p-EGFR Tyr992 was significantly associated with both cMET and p-cMET among TN cases (p<0.05), but not among HER2 positive breast cancer." (PMID 27055285, 2016). "In future studies, it will be important to determine the threshold of EGFR expression required to initiate the killing by EGFR-CAR NK cells, as others have found that expression levels of wtEGFR can vary over a three log range in breast cancer patient samples and cell lines." (PMID 27050072, 2016). "Furthermore, the knockout of EGFR (or IGF-IR) abolished the E2-proliferative response in mice, and the inhibition of EGFR activity suppressed the proliferative effect of E2 in breast cancer cells in vitro." (PMID 26258011, 2015). "Several authors have suggested anti-EGFR treatment to be ineffective due to the largely negative results obtained during phase II studies performed with gefitinib in breast cancer cohorts." (PMID 26267891, 2015). "The present study suggests that EGFR protein overexpression, as assessed by IHC, is a negative prognostic factor for OS and DFS in patients with high-risk operable breast cancer." (PMID 26021752, 2015). "The clinical significance of these findings in the context of breast cancer is that IGFBP-3 and EGFR are relatively highly expressed in some aggressive ER-negative and PR-negative tumors that lack amplification of HER2, which are now referred to as triple-negative breast cancers, or TNBC." (PMID 26221601, 2015). "In breast cancer for instance, patients with tumors that are estrogen receptor (ER) and epidermal growth factor receptor (ErbB2) negative are less responsive to hormone based treatment than those possessing active receptors." (PMID 25965340, 2015). "This is because the Her-2-ER interaction is also associated with the anti-hormone resistance and PTPH1 can decrease Her-2/Y877 phosphorylation (data not shown) and increase breast cancer sensitivity to the EGFR/Her-2 dual inhibitor Lap." (PMID 26079946, 2015). "In this study, we investigate in vitro and in vivo efficacy of cetuximab (cet)-IR700 NIR-PIT on two breast cancer models MDAMB231 (TNBC, EGFR moderate) and MDAMB468 (TNBC, EGFR high) cell lines, and demonstrate a method to optimize the dosing APC and NIR light." (PMID 26313651, 2015). "Indeed, development of targeted therapy against EGFR/ERBB2, such as a lapatinib, have significantly improved treatment of ERBB2-positive breast cancer." (PMID 25596742, 2015).